MIR554 (microRNA 554)
Synonyms: hsa-mir-554; MIRN554
Gene: MicroRNA gene on chromosome 1 (151,545,796 to 151,545,891, forward strand). Ensembl gene ENSG00000207606.
Gene Ontology:
Biological process: miRNA-mediated post-transcriptional gene silencing
Homologues: Orthologues: chimpanzee ptr-mir-554 (100% identical), macaque mml-mir-554 (95% identical).